LINC01535 (long independently transcribed non-coding RNA 1535)
Gene: Long non-coding RNA gene on chromosome 19 (37,251,448 to 37,267,879, forward strand). Ensembl gene ENSG00000226686.
Diseases named in the same sentence as LINC01535 in open-access papers:
LINC01535 is named in the same sentence as 11 diseases in open-access papers, as found by Europe PMC text mining. Sharing a sentence is not in itself a finding about the gene and the disease. The quoted sentences say what the papers report.
cervical cancer (2 papers, 2019 to 2024). A primary or metastatic malignant neoplasm involving the cervix. "Existing reports show that LINC01535 expression is dysregulated and that LINC01535 acts as an oncogene in various cancers, such as cervical cancer, osteosarcoma and esophageal squamous cell cancer 10-13." (PMID 38911365, 2024). "Consistent with the down‐regulation of miR‐214 by LINC01535, the expression of miR‐214 was significantly reversely correlated with that of LINC01535 in cervical cancer tissues (r = −0.5615, P < 0.0196)." (PMID 31273925, 2019). "High expression of LINC01535 is associated with advanced FIGO stage, lymph node metastasis and poor survival of cervical cancer patients." (PMID 31273925, 2019). "Our findings suggest LINC01535 as a novel candidate for the prognosis and therapy of cervical cancer." (PMID 31273925, 2019). "Kaplan‐Meier analyses in these 80 cervical cancer cases presented that increased LINC01535 high expression was correlated with worse overall survival (P = 0.0196)." (PMID 31273925, 2019). "We investigated the expression and roles of LINC01535, and resolved in detail, the mechanisms of action of LINC01535 in cervical cancer." (PMID 31273925, 2019). "Results of functional experiments indicated that enhanced expression of LINC01535 promotes cervical cancer cell growth, migration and invasion in vitro, and cervical cancer xenograft growth in vivo." (PMID 31273925, 2019). "Next, we further investigated the implications of targeting LINC01535 for cervical cancer." (PMID 31273925, 2019). "To determine whether the oncogenic roles of LINC01535 in cervical cancer are dependent on the repression of miR‐214/EZH2 regulatory loop, we stably overexpressed miR‐214 or stably silenced EZH2 in LINC01535 stably overexpressed HeLa cells." (PMID 31273925, 2019). "In addition, the expression of LINC01535 is inversely associated with that of miR‐214 and positively associated with that of EZH2 in cervical cancer tissues, which support the negative regulation of miR‐214/EZH2 loop by LINC01535." (PMID 31273925, 2019).
clear cell renal cell carcinoma (2 papers, 2022 to 2023). "LINC01535 affects clear cell renal cell carcinoma progression by mediating PI3K/Akt signaling through the LINC01535/miR–146b-5p/TRIM2 axis, corresponding to the LINC01535/miR-146b-5p binding pair predicted in this study." (PMID 37325630, 2023). "Nevertheless, the expression pattern and potential roles of LINC01535 in clear cell renal cell carcinoma (ccRCC) remain to be elucidated." (PMID 35342411, 2022).
osteosarcoma (2 papers, 2022 to 2024). A usually aggressive malignant bone-forming mesenchymal neoplasm, predominantly affecting adolescents and young adults. "For instance, LINC01535 was demonstrated to exert a pregnant regulation in osteosarcoma development." (PMID 35342411, 2022).
colorectal cancer (1 paper, 2022). A primary or metastatic malignant neoplasm that affects the colon or rectum. "LINC01535 was also observed to be aberrantly expressed in colorectal cancer and subsequently affected the cancer progression." (PMID 35342411, 2022).
gastric cancer (1 paper, 2024). A primary or metastatic malignant neoplasm involving the stomach. "The expression levels of LINC00853, LINC00634, LINC01535, GAPLINC, and AC017002.1 were significantly higher in gastric cancer tissues than in non-cancerous adjacent tissues (P ≤ 0.05), confirming that these five lncRNAs were differentially expressed in the EGC samples." (PMID 38586313, 2024).
ovarian carcinoma (1 paper, 2020). A malignant neoplasm originating from the surface ovarian epithelium. "As a consequence, FUT8-AS1, LINC00665 and LINC01535 were identified as key upstream lncRNAs of the ceRNA network in ovarian cancer." (PMID 33123295, 2020).
viral meningitis (1 paper, 2024). Inflammation of the membranes surrounding the brain and spinal cord due to a viral infection. "In viral meningitis specific co-expression networks, a total of 9 significantly upregulated lncRNAs (AC243830.1, AC092111.1, CEROX1, AC246817.2, FAM66C, LINC01535, LINC02848, CHKB-DT, and C18orf15) were identified." (PMID 38347610, 2024).
cancer (2 papers, 2022 to 2024). A tumor composed of atypical neoplastic, often pleomorphic cells that invade other tissues. "Here, we observed a novel lncRNA transcript, LINC01535, which has been reported in many studies on cancers." (PMID 35342411, 2022). "LINC01535, belonging to the lncRNA family, was reported to have an aberrant expression in certain types of cancers and thus affect cancer progression." (PMID 35342411, 2022). "LINC01535, belonging to the lncRNA family, was found having an aberrant expression in certain types of cancers and thus affects the biological processes of these cancers." (PMID 35342411, 2022). "LINC01535 was reported to have, in certain cancers, an aberrant expression." (PMID 35342411, 2022).
tumor (2 papers, 2022 to 2024). "In addition, upregulation of LINC01535 significantly decreased the expression of microRNA-214-3p (miR-214-3p), which was found closely associated with suppressing tumor progression." (PMID 38911365, 2024). "LINC01535 knockdown suppressed tumor growth, while LINC01535 overexpression accelerated tumor growth." (PMID 38911365, 2024). "Moreover, LINC01535 upregulation attenuated in vitro ccRCC development and hindered in vivo tumor growth." (PMID 35342411, 2022). "Besides, LINC01535 upregulation attenuated in vitro ccRCC progression and hindered in vivo tumor growth." (PMID 35342411, 2022).
LINC01535 also shares sentences with these, for which no sentence is quoted: esophageal squamous cell carcinoma (1 paper); lymph node metastasis (1).